Y_RNA (Y RNA )
Gene: Miscellaneous RNA gene on chromosome 2 (62,726,636 to 62,726,740, reverse strand). Ensembl gene ENSG00000252436.
Homologues: Orthologues: chimpanzee Y_RNA (100% identical). Paralogues in human: RNY1 (85% identical), Y_RNA (85% identical), Y_RNA (84% identical), RNY1P8 (82% identical), Y_RNA (82% identical), RNY1P11 (81% identical), Y_RNA (81% identical), Y_RNA (80% identical), RNY1P10 (79% identical), Y_RNA (79% identical), Y_RNA (78% identical), RNY1P12 (77% identical), and 96 more.